ULK1 (unc-51 like autophagy activating kinase 1)
Diseases named in the same sentence as ULK1 in open-access papers (continued):
Sharing a sentence is not in itself a finding about the gene and the disease.
cancer (continued). "However, when compared to non‐resistant cancer cells (i.e., LSCC), only two of them, namely, ATG3, and ULK1 were upregulated, whereas the other three were downregulated in DR‐LSCC." (PMID 40385549, 2025). "Additionally, ULK1/2 inhibitors, such as SBI-020696569 and DCC-311670, have shown effectiveness in blocking autophagy initiation, offering targeted approaches for cancer treatment." (PMID 39865083, 2025). "In addition to ULK1, overexpression of LUCAT1 further elevated the LC3-II/LC3-I ratio and decreased p62 levels to promote cancer cell autophagy." (PMID 35379783, 2022). "Finally, ULK1 is a core component of the autophagy pre-initiation complex and ULK1 inhibitors such as ULK-101 and others have been developed with a view to inhibiting autophagy as a cancer therapeutic approach." (PMID 34654847, 2021). "Not surprisingly, ULK1 results upregulated in several human diseases, including cancer, and counteracting its activity seems to be a promising anti-cancer treatment." (PMID 34830777, 2021). "AMPK has been shown to activate Unc-51-like kinase 1 (ULK1), a key initiator of autophagy, through phosphorylation and inhibition of mammalian target of rapamycin complex 1 (mTORC1) activity, leading to the induction of autophagy in cancer cells." (PMID 33299639, 2020). "Surprisingly, ULK1 activation (phosphorylation at S555) by cancer requires p38β MAPK, rather than AMPK." (PMID 31225455, 2018). "Among all the tested cancer cell lines, AGS cells expressed highest level of Ulk1." (PMID 28410240, 2017). "We propose that activation of the phosphatase activity towards ULK1 represents a mechanism that allows cancer cells to activate a strong autophagy flux without turning off mTOR activity, thus achieving optimal growth and survival capability." (PMID 26310906, 2015). "That ULK1-dependent autophagy can be promoted by stimulating the protein phosphatase targeting ULK1 without suppressing mTORC1 can explain the seemingly contradictory co-existence of intact mTORC1 function and strong autophagy activity in various cancers." (PMID 26310906, 2015). "In contrast, the effect of ULK1/2 inhibition has been questioned since abrogation of ULK1/2-mediated autophagy could not block extracellular protein-dependent cancer cell growth." (PMID 35237600, 2022). "Here, we examined whether ULK1 complex component autophagy-related protein 101 (ATG101) is downregulated via ubiquitination, and whether this in turn suppresses autophagy activity in cancer cells." (PMID 34502089, 2021). "Similarly, shNEDD4L cells were sensitized to pharmacological inhibition of ULK1 or ASCT2, as well as to the blockade of mitochondrial OXPHOS when compared to shCTL cells, suggesting that NEDD4L-knockdown cancer cells rely on mitochondrial metabolism to sustain cell growth and survival." (PMID 31959741, 2020). "Moreover, double knockout (DKO) of ULK1 and ATG13 could block cell cycle progression and significantly decrease cancer cell proliferation in cell line and mouse models." (PMID 32516310, 2020). "The data verification results of the HPA database indicated that the expression of ULK1 in cancer and adjacent tissues had not been detected in the database, and the expression of the remaining seven genes in cancer and adjacent tissues could be verified." (PMID 33324651, 2020). "Studies testing Ulk1 expression in cancer cells have not been able to reach consistent conclusion." (PMID 28410240, 2017).
cancer (continued). "Here, we examined whether the ULK1 complex component ATG101 is also regulated by ubiquitination, and conducted additional experiments to identify the types of ubiquitin-conjugation and enzymes involved, as such information could help define therapeutic targets for autophagy modulation in cancer." (PMID 34502089, 2021). "Considering that TRPML1-mTORC1 downregulates autophagy through inhibiting ULK1 and VPS34 complex, and that TRPML1-AMPK upregulates autophagy through activating ULK1 and VPS34 complex, TRPML1 may coordinate both mTORC1 and AMPK signaling pathways to regulate cancer development at different stages." (PMID 33419007, 2021). "Also, an exhaustive description of ULK1 alterations found in cancer samples is presently lacking." (PMID 32913252, 2020). "STK38 is implicated to suppress the transcription of ULK1, we then explored the expressions of STK38, ULK1 and p-ULK1 in the absence of Caprin-1 or/and STK38 cancer cells." (PMID 38082307, 2023). "Considerable work has been done to develop inhibitors for ULK1/2, ATG7, and vps34, but most of these have not been further developed for anti-cancer treatments, mainly because of toxicity." (PMID 31878323, 2019). "Most recently, a ULK1 inhibitor which inhibits autophagic flux in a non-lysosomal manner has entered a clinical trial that will eventually be used in combination with a MEKi in RAS and RAF mutant cancers (NCT04892017)." (PMID 34830283, 2021). "In other cancer types, ULK2 could compensate for ULK1 downregulation and, in the majority of the cases, no marked changes in expression have been found." (PMID 32913252, 2020). "Indeed, recent studies in skeletal muscle and cancer cells reported that pharmacological activation of REV-ERBα inhibits autophagosome formation via negative modulation of core autophagy genes such as Ulk3, Ulk1, Bec1, Atg7, and Atg5." (PMID 35428762, 2022).
infection (72 papers, 2013 to 2026). The state of being infected such as from the introduction of a foreign agent such as serum, vaccine, antigenic substance or organism. "The most recent study regarding the interplay between HPV16 and autophagy in HNSCC, reported an increase of O-linked β-N-acetylglucosamine (O-GlcNAc) at Ser409 in ULK1 upon infection with HPV16 E6/E7-expressing lentiviral constructs." (PMID 38291202, 2024). "We used HRM qRT-PCR to confirm the presence of mutated Ulk1 and Ulk2 RNAs transcripts after the infection with the gRNAs." (PMID 32985978, 2020). "Of note, the protein loss of ULK1 was accompanied by the emergence of lower molecular weight fragments (~ 75 kDa) at ~ 8 h post-infection." (PMID 33149253, 2020). "CLSM imaging quantitation also showed decreased LC3 puncta by ULK1 deficiency upon Pa infection." (PMID 26735693, 2016). "ULK1 expression significantly increased post-infection, whereas genetic silencing of ULK1 reduced LC3-II conversion." (PMID 41924479, 2026). "More importantly, and the second key finding of this study, is that ULK1/2 inhibition was able to preserve mitochondrial polarization during infection." (PMID 39791872, 2025). "We demonstrated that exogenous AbOmpA inhibited autophagy by suppressing AMPK phosphorylation at Thr172 and ULK1 phosphorylation at Ser317, while inducing mTOR under both infection and starvation stress conditions." (PMID 39998213, 2025). "At 4 h post-infection, we found that ~73% versus~22% of bacteria were positive for ubiquitin and ~57% versus ~13% positive for p62 in wild-type versus ULK1 KO MEFs, respectively." (PMID 40853005, 2025). "In hTCEpi cells, phosphorylated levels of mTOR, S6, and ULK1 were all decreased 2 hours post infection." (PMID 39791872, 2025). "Using a standard invasive test strain of PA, we show that PA infection triggers dephosphorylation of the mechanistic target of rapamycin in corneal epithelial cells, leading to the induction of autophagy through ULK1/2." (PMID 39791872, 2025). "We established A2780 and ES-2 cell lines with stable ULK1 overexpression through lentiviral infection." (PMID 38286802, 2024). "To further investigate the mTOR and autophagy status during TGEV infection, we infected PK-15 cells with TGEV and monitored the phosphorylation of mTOR and its downstream factor ULK1 at 8 and 12 hours post-infection." (PMID 37377422, 2023). "Of note, infection by T. gondii significantly inhibited starvation-induced transcription of autophagy-related genes (i.e., ULK1, BECN1, PINK1, GABARAPL2, SQSTM1, and NBR1), as compared to uninfected serum-starved HFF cultures (i.e., “Control”)." (PMID 37387601, 2023). "Levels of p-ULK1 remained constant during the first 4 hpi of infection and then rose slightly compared to mock infected cells up to 16 hpi suggesting up regulation of mTORC1 by ASFV." (PMID 34406116, 2021). "Meanwhile, as the core protein of the autophagy signaling pathway, total and phosphorylated levels of ULK1 were increased after infection." (PMID 33600403, 2021). "H37Ra infection leads to downregulation of miR-106a in a time- and dose-dependent manner and concomitant upregulation of its three targets (ULK1, ATG7, and ATG16L1) in THP-1 macrophages." (PMID 33505399, 2020). "Intracellular survival of GAS at 6 h after infection was increased in ULK1-depleted cells, indicating that ULK1 is required to eliminate the intracellular GAS." (PMID 32034138, 2020). "ULK1 plays an important role in protecting hosts from infection by pathogens; inhibition of ULK1 expression prevents the death of host cells infected by Staphylococcus aureus." (PMID 32033142, 2020). "The level of ULK-1 protein was significantly correlated with the number of AIEC LF82 bacteria at 10 h post-infection within AIEC LF82-infected MDM from CD patients (ρ = 0.37; p = 0.033)." (PMID 31694333, 2019).
infection (continued). "Infection with Mfa1-positive P. gingivalis strains induced expression of p-mTOR, p-ULK1 and Raptor, consistent with the conclusion that p-Akt activation blocks autophagy induction." (PMID 31608069, 2019). "During SLO mutant strain infection, the presence of β1 integrin on LC3-associated vacuoles significantly diminished, accompanied by increasing recruitment of ULK1 and decreasing expression of NOX2 on LC3-positive GAS." (PMID 31575768, 2019). "We observed a reduced survival ability of AIEC LF82 at 1 h and 6 h post-infection within MDM transfected with siRNA targeting ULK-1 compared to those transfected with scramble siRNA (p = 0.0157 and p = 0.0018, respectively)." (PMID 31694333, 2019). "Host kinases in the IRE1α-ULK1 axis, including IRE1α, ASK1, JNK1, and/or AMPKα as well as ULK1, were also coordinately phosphorylated in an IRE1α-dependent fashion upon the pathogen infection." (PMID 29732320, 2018). "To test this possibility, we infected Ern1wt/wt and Ern1mut/mut BMDMs with Bm16M and monitored phosphorylation level of ULK1 during a time course of 48 h of infection." (PMID 29732320, 2018). "The level of phosphorylated ULK1-Ser757 decreased during mid-infection and was only negligibly present at the terminal stage, a pattern that suggested a close relationship of the phosphorylated protein with altered endogenous mTOR." (PMID 26423766, 2015). "Similarly, while the inhibition of ULK1/2 impaired autophagy, it appeared to be mitoprotective during PA infection." (PMID 39791872, 2025). "Moreover, autophagy is modulated through the mTORC1/ULK1 signaling pathway during orthoflavivirus infection to provide a platform for viral RNA replication and virion maturation." (PMID 40270809, 2025). "Importantly, we show that PA not only exploits autophagy in corneal epithelial cells, but we provide evidence supporting a novel role for ULK1/2 in mediating the mitochondrial response during infection in the cornea." (PMID 39791872, 2025). "During PA infection, the inhibition of ULK1/2 downregulated both purine and pyrimidine metabolism." (PMID 39791872, 2025). "Collectively, these data suggest that the inhibition of ULK1/2 may be mitoprotective to corneal epithelial cells during infection." (PMID 39791872, 2025). "Similarly, a decreased DENV infection was observed after silencing of Atg13 or FIP200, suggesting that ULK-1-dependent autophagy supports infection of DCs." (PMID 38863700, 2024). "This elucidates the potential role of RB1CC1 and ULK1 in early infection with SARS-CoV-2 and illuminates how NIC may regulate autophagy." (PMID 37901834, 2023). "Infection with P. bovis increased protein expression levels of AMPKα, p-AMPKα, ULK1, p-ULK1 and LC3II/LC3I, but decreased SQSTM1/p62 protein expression in bMECs compared to the control group, suggesting that autophagy induced by P. bovis was activated in bMECs." (PMID 36148236, 2022). "As ULK1 is the autophagy initiating kinase, these results suggest that autophagy, known to engulf intracellular microbes upon infection, could be playing a protective role by engulfing the invading HPV particles, thus protecting patients from HNSCC." (PMID 35931119, 2022). "Indeed, mTORC1-dependent phosphorylation of ULK1 at S757 was maintained around the basal level throughout the course of infection (ULK1S757), suggesting that SARS-CoV-2 avoids triggering starvation-induced autophagy." (PMID 34155207, 2021). "As ULK-1 activity is dependent on phosphorylation, we showed a significant decrease of the ratio p-ULK-1 on Serine 757/total ULK-1 within macrophages from CD patients following AIEC infection compared to uninfected macrophages, UC patients and healthy volunteers." (PMID 31694333, 2019). "We also tested whether several host autophagy-related components, including Atg1 (ULK1), Atg2, Atg18 (WIPI1), Atg9 and Beclin 1, conferred susceptibility to Bm16M infection via CFU assay and image-based host cell infection analysis." (PMID 29732320, 2018).
infection (continued). "Ulk1 protein and Ulk1 mRNA were both decreased after infection of the shRNA." (PMID 28410240, 2017). "Increases in brain AMPK and ULK1 occurred at an early stage of agent 263 K infection." (PMID 26423766, 2015). "It is interesting to note that while ULK1 deficiency and blockade of p62 S409 phosphorylation deeply affected the host cell’s ability to recruit Ub and p62 during the infection with the wild-type strain, it did not impact the presence of these two proteins on the surface of ΔactA L. monocytogenes." (PMID 40853005, 2025). "In addition, ULK1 co-localized with BCVs following infection." (PMID 29732320, 2018). "To test whether Bm16M-induced activation of ULK1 could also occur through the activation of AMPKα, we examined the phosphorylation AMPKα in the Ern1wt/wt or Ern1mut/mut BMDMs during a time course of Bm16M infection." (PMID 29732320, 2018). "However, Bm16M infection enhanced the phosphorylation of ULK1 on Ser555." (PMID 29732320, 2018). "Consequently, we concluded that the abundance of miR-142-5p could repress Ulk1 mRNA, resulting in limited synthesis of new Ulk1 protein and restricted neuronal morphogenesis in underlying PHEV infection." (PMID 28516065, 2017). "To determine whether the autophagy pathway can be induced upon RGDV infection, we first monitored the expression of 3 autophagy-related genes (Ulk1/Atg1, Atg5 and Atg8) in continuous cultured vector cells in a monolayer (VCM) derived from R. dorsalis using an RT-qPCR assay." (PMID 29125860, 2017). "At 24 h and more prominently at 48 h post-infection, B. neotomae-infected cells treated with ENBA or cilostamide exhibited increased phosphorylation of AMPK (Thr172) and ULK1 (Ser317) relative to untreated wild-type infection." (PMID 41542404, 2026). "MRT68921, an inhibitor of autophagy-activating kinase ULK1, showed antiviral activity against H3N2 and H5N1 (SI > 2), and decreased pH1N1 infection (SI < 2)." (PMID 37758692, 2023). "Further analysis in MRC-5 cell line showed that, in the context of infection, MERS-CoV-MA 4b inhibited autophagy, as confirmed by the increase of p62 and the decrease of ULK1 protein levels, either by direct or indirect mechanisms." (PMID 36129908, 2022). "Infection of RAW 264.7 macrophages with ΔPE_PGRS20 and ΔPE_PGRS47 resulted in increased Atg5 and decreased p62 (SQSTM1) and phospho-Unc-51-like autophagy-activating kinase 1 (Ulk1) compared to wild-type M. tuberculosis infection." (PMID 34346699, 2021). "Our study showed that the expression of autophagy-related genes ULK1, ATG13, ATG101, Beclin-1, ATG14, MAP1LC3A, and MAP1LC3B was significantly increased and that SQSTM1 was decreased in the muscle with pathogen infection." (PMID 33574492, 2021). "To examine if TBC1D9 is also required for the recruitment of ULK1 to the invading GAS, we observed the ULK1 localization during infection." (PMID 32034138, 2020). "Stimulation of human macrophage-like cells with the P90A virus protected them against subsequent infection with an otherwise resistant wild type HIV-1 in a manner requiring TRIM5α, BECN1, and ULK1." (PMID 33052966, 2020). "More importantly, we show that, in ULK1-KO MEFs, bacteria are not efficiently ubiquitylated, and p62 is not targeted to the bacterial surface throughout infection with L. monocytogenes." (PMID 40853005, 2025). "The key regulators of autophagy include the ATG1/ULK1 and PI3K protein kinase complexes, with mTORC1 acting as a critical switch in autophagy when inhibited under stress conditions such as starvation or intracellular pathogen infection, activating autophagy." (PMID 40869159, 2025). "We also investigated the impact of VgrG2 on the mTOR signaling pathway by examining the transcription levels of key genes, including mTOR, ULK1, Beclin-1, P62, LC3, Atg3, Atg5, and Atg12, following infection, and assessed the expression of the autophagy marker protein LC3-II." (PMID 40266908, 2025).